ENSG00000270099 (novel transcript)
Gene: Protein-coding gene on chromosome 10 (95,860,548 to 95,924,844, forward strand). Ensembl gene ENSG00000270099.
Genetic constraint (gnomAD): Missense variants: 54 observed, 68.75 expected, observed/expected ratio (o/e) 0.79, 90% interval 0.63 to 0.99. Synonymous variants: 23 observed, 23.37 expected, observed/expected ratio (o/e) 0.98, 90% interval 0.71 to 1.39.